ENG (endoglin)
Diseases named in the same sentence as ENG in open-access papers (continued):
Sharing a sentence is not in itself a finding about the gene and the disease.
glioma (24 papers, 2010 to 2025). A benign or malignant brain and spinal cord tumor that arises from glial cells (astrocytes, oligodendrocytes, ependymal cells). "Next, endoglin mRNA expression was determined in a panel of 13 human glioma cell lines, 8 LTC and 5 GIC." (PMID 33471197, 2021). "Endoglin gene silencing in T98G glioma cells and in human cerebral microvascular endothelial cells (hCMEC) did not affect constitutive or exogenous TGF-β superfamily ligand-dependent signaling, except for a minor facilitation of pSmad1/5 signaling in hCMEC." (PMID 33471197, 2021). "Our study showed a significantly higher endoglin expression in U87 glioma cells than in Hs5 fibroblasts." (PMID 33419226, 2021). "In a similar approach, tumor margins in a glioma rat model (C6 cell line) were effectively delineated by targeting endoglin with paramagnetic liposomes conjugated to monoclonal anti-CD105 antibodies." (PMID 33946583, 2021). "Taken together, the ELISA data confirm the cytokine array findings and implicate PDGF-AA, CHI3L1, IL-8, and ENG as secreted factors under negative regulatory control by neurofibromin in a subset of glial tumor cell lines in vitro." (PMID 29643433, 2018). "Analysis of The Cancer Genome Atlas confirmed a relationship between glioma NF1 status and ENG and CHI3L1 in tumor samples." (PMID 29643433, 2018). "However, we did not detect an upregulation of endoglin by flow cytometry in a human LTC (LN-18) or GIC (ZH-161) glioma cell line after culturing under hypoxia compared with normoxia." (PMID 33471197, 2021).
renal cell carcinoma (24 papers, 2014 to 2025). "Endoglin has previously been suggested as a cancer stem cell (CSC) marker in renal cell carcinoma (RCC)." (PMID 37396898, 2023). "Endoglin or CD105 is a membrane marker of tumor endothelial cells but has also been described as a potential cancer stem cell marker in renal cell carcinoma as well as other cancers." (PMID 30551640, 2018). "For renal cell carcinoma, several potential markers have been discussed, including CXCR4, CD105 or endoglin, and CD133 which correlate with poor prognosis." (PMID 30551640, 2018). "In this work, we generated from renal cell carcinoma CSC-derived and tumor-derived endothelial cells expressing the surface glycoprotein CD105 (Endoglin) and tested the effect of TRC105, a CD105 monoclonal antibody, on the angiogenic properties of these tumor endothelial cells (TEC)." (PMID 29854307, 2018).
hereditary hemorrhagic telangiectasia type 1 (23 papers, 2010 to 2025). "The results of the blood whole-exome sequencing revealed a pathogenic heterozygous splice site variant (c.511C > T) in the endoglin gene, an evidence of hereditary hemorrhagic telangiectasia type 1 (HHT1)." (PMID 38907280, 2024). "The intricacy of endoglin-mediated mechanisms is illustrated by a specific subtype of Rendu–Osler–Weber disease: hereditary hemorrhagic telangiectasia type 1 (HHT1)." (PMID 33946583, 2021).
Stroke (23 papers, 2003 to 2025). Sudden impairment of blood flow to a part of the brain due to occlusion or rupture of an artery to the brain. "Correspondingly, heterozygous ENG-deficient mice subjected to permanent MCAO had larger stroke volumes and were more severely impaired than wild-type animals." (PMID 35806090, 2022). "Various studies revealed the role of ENG in preventing hypoxia-induced EC death and in promoting vascular stability, while ENG deficiency was linked with poorer outcomes in stroke models, demonstrating its major role in post-ischemic vascular remodelling and recovery." (PMID 39684220, 2024). "Animal studies showed that ENG deficiency impairs stroke recovery." (PMID 29098173, 2017). "Among these, three are likely monogenic causes of stroke (ELN, SCN5A, and VHL genes), two are considered risk factors (FV and ADAMTS13), two have conflicting interpretations (ACAD9 and ENG), and three are most likely benign (CBS, PMM2, and PKD1)." (PMID 40650005, 2025). "For one, mCRP colocalizes with a marker of angiogenesis (i.e., endoglin [CD105]) in stroke patients, suggesting a potential relationship in vivo." (PMID 40093010, 2025). "To corroborate our in vitro finding that the sequence of hypoxia followed by reoxygenation, but not hypoxia alone, induced shedding of ENG, we next investigated ENG expression in a murine stroke model." (PMID 35806090, 2022). "First, we subjected confluent HBMEC monolayers to quantitative real-time PCR and Western blot analysis, since the upregulation of ENG after hypoxia was described in other vascular beds and post-mortem sections of stroke patients." (PMID 35806090, 2022). "Analogously, ENG is upregulated in hypoxic tissue in post-mortem sections of patients with stroke and in the ischemic brain tissue of mice." (PMID 35806090, 2022). "ENG deficiency is associated with the development of AVM in HHT patients, exacerbates stoke injury and impairs stroke recovery." (PMID 29098173, 2017). "Preclinical studies showed that increasing circulating CD105+ (endoglin, a surface marker of MSCs) MSCs by exogenous administration was effective in recovery after stroke." (PMID 22615882, 2012). "Endoglin, has also been reported to be highly expressed in human hearts with severe left ventricular systolic dysfunction and with major adverse cardiovascular events like congestive heart failure, acute myocardial infarction, stroke, and sudden cardiac death." (PMID 36720768, 2023). "The monomeric form of CRP was found to be colocalized with the angiogenetic marker endoglin (CD105) in stroke cases and found to stimulate ERK1/2 phosphorylation, resulting in cell migration and the creation of tube-like structures, regardless of the CD16 axis." (PMID 37873776, 2023). "Moreover, they reported a correlation with stroke severity, with ICAM-1+ EVs (CD105+, CD54+, CD45– (leukocyte marker)) being most strongly correlated with infarct volume and endoglin+ EVs (CD105+, CD41a–, CD45–) correlating with long-term clinical outcome." (PMID 36009857, 2022).
Telangiectasia (23 papers, 2012 to 2024). Telangiectasias refer to small dilated blood vessels located near the surface of the skin or mucous membranes, measuring between 0.5 and 1 millimeter in diameter. "HHT is a rare condition characterized by telangiectasia and congenital AF, and is caused by mutations in endoglin/CD105 and activin receptor-like kinase-1 (ALK1)." (PMID 34541367, 2021). "Endoglin expression levels were found to be exceptionally low in skin, a tissue with notably high prevalence of telangiectases even at young age." (PMID 34445652, 2021). "Patients with elevated soluble endoglin levels more frequently had telangiectasia than did those with normal soluble endoglin levels." (PMID 33105647, 2020). "Mechanistic studies on HHT have been performed in endoglin heterozygote mice, which, in contrast to endoglin-knockout mice, are viable and show signs of HHT, such as telangiectasias and nosebleeds, after a prolonged period of time." (PMID 32059544, 2020). "We identified a pathogenic somatic second hit from at least one telangiectasia sample from every individual with a germline mutation in ACVRL1, and none of the individuals with a germline mutation in ENG." (PMID 39062925, 2024). "In stark contrast, telangiectases seen in HHT patients with ACVRL1, ENG, or SMAD4 mutations are overwhelmingly punctate (not spidery) and typically occur on the lips and oral cavity, not other aspects of the face." (PMID 33834622, 2021).
atherosclerosis (22 papers, 2009 to 2025). A disease characterized by the build-up of fatty material and calcium deposition in the arterial wall resulting in partial or complete occlusion of the arterial lumen. "were the first to demonstrate that soluble endoglin (sEng) levels were elevated in patients with atherosclerosis, especially in those with peripheral artery disease, and positively correlated with total cholesterol levels." (PMID 39931738, 2025). "Endoglin is indispensible for normal angiogenesis, so its expression is up-regulated during healing of wounds, atherosclerosis, inflammation, hypoxia, and vascular injury as well as in developing embryos." (PMID 35285425, 2022). "This study aimed to clarify the pathophysiological effects of endoglin on the development of atherosclerosis and to explore the mechanism of the signalling pathway." (PMID 34602076, 2021). "The aim of this study was to reveal the physiological role and signalling mechanisms of endoglin in the development of blood lipid-mediated atherosclerosis." (PMID 34602076, 2021). "Although the numbers are limited, the existing studies support the potential of endoglin-based (PET) imaging of angiogenesis in atherosclerosis, in aortic aneurysm, and after myocardial infarction." (PMID 33946583, 2021). "All these findings suggest the participation of the endothelial receptors ALK1 and endoglin in the regulation of atherosclerosis, mainly exerting an antiatherogenic effect." (PMID 32523017, 2020). "Supporting this view, endoglin has been shown to be upregulated in vivo in several inflammatory settings, including wound healing, atherosclerosis and chronic kidney disease." (PMID 29080903, 2018). "A recent clinical study has revealed that the expression of endoglin is increased in patients with atherosclerosis and that the endoglin level is thought to predict CV events in patients with chronic coronary artery disease after PCI." (PMID 28936254, 2016). "Although investigated to a lesser extent than HHT1 and cancer, the role of endoglin in atherosclerosis, specifically in endothelial cell activation, vascular remodeling, angiogenesis, and inflammatory cell migration, suggest that the protein is a versatile imaging target." (PMID 33946583, 2021). "Therefore, it remains unclear among the current academic community whether the protective effect of endoglin is a biological target for atherosclerosis." (PMID 34602076, 2021). "Endoglin is expressed at high levels in ECs undergoing active proliferation or angiogenesis, while its levels in VSMCs are very low or undetectable in normal conditions, but they can be increased upon in vitro culture, during atherosclerosis or vascular injury." (PMID 26646071, 2016).
diabetes (20 papers, 2010 to 2025). "Through regression analysis, we found that METS value was associated with endoglin level, age, history of diabetes." (PMID 36523357, 2022). "Among other baseline and demographic characteristics, only the presence of diabetes (β = 0.47, P = 0.04) was significantly associated with circulating endoglin concentration." (PMID 21886815, 2011). "Of the top differentially altered proteins linked with NOX4OE, endoglin and SERPINE1 (outlined in red) were considered to be most relevant to CB-ECFC function in diabetes due to their established pro-angiogenic actions." (PMID 40457435, 2025). "Another research group investigated the role of endocan and another glycoprotein, endoglin, in CKD caused by diabetes mellitus." (PMID 32854332, 2020). "The results indicated that both endocan and endoglin levels were higher in diabetes mellitus patients than in the control group." (PMID 32854332, 2020). "Although we have not found any significant relationship or correlation between Sol-endoglin and renal dysfunction, endoglin levels were higher in patients with diabetes with three or more target organs damaged than in those with no organs affected." (PMID 21171985, 2010). "Patients with diabetes show increased plasma levels of soluble endoglin." (PMID 35327565, 2022). "As intra-islet blood vessel is important for glucose sensing and insulin distribution, whether endothelia-specific endoglin would play a role in islet function in stressed conditions, such as diabetes, could be an interesting issue." (PMID 35327565, 2022). "The association between endoglin and CKD was also non-significant when the analysis was restricted to women (P = 0.21) or to the subgroup of individuals with diabetes (P = 0.28)." (PMID 21886815, 2011). "On the other hand, we also observed a positive correlation between heart rate and plasma Sol-endoglin in nonhypertensive patients with diabetes." (PMID 21171985, 2010). "Moreover, nonhypertensive patients with diabetes with extreme dipper pattern showed higher plasma levels of Sol-endoglin than did dipper, nondipper and riser groups, and endoglin showed a negative correlation with systolic night-day ratio in these patients." (PMID 21171985, 2010). "Thus, endoglin levels were higher in all patients with diabetes with nondipper (absence of the normal nocturnal fall in blood pressure) and extreme dipper (with marked nocturnal blood pressure falls) than in dipper circadian patterns." (PMID 21171985, 2010).
pancreatic cancer (20 papers, 2013 to 2025). "P/LP variants of APC, BRCA2, BUB1B and ENG were identified in patients with pancreatic cancer, and MSH6 was identified in an NPaMC patient with both colorectal and esophageal cancers." (PMID 36896836, 2023). "The authors also indicated that deletion of the ENG gene specifically in collagen type 1α1‐expressing stromal cells resembling CAFs produced very little inhibition of the growth of murine pancreatic cancer cells injected orthotopically into mice." (PMID 40644310, 2025). "ENG, a homodimeric transmembrane glycoprotein expressed in the LECs in pancreatic cancer, consists of immature endothelial cells induced by tumor lymphangiogenesis." (PMID 36067135, 2022). "Coculture of CSC with a subpopulation of endoglin-expressing pancreatic cancer cells (CD105) has been reported to increase the proportion of CD105-positive cancer cells and these cells present higher migration activity compared to CD105-negative cells." (PMID 33466892, 2021). "APC, BRCA2, BUB1B, ENG and MSH6 were associated with cancer predisposition, and pathogenic/likely pathogenic (P/LP) variants occurred in 6% [pancreatic cancer (4/72); all-cancer (5/90)] and 54% (49/90) carried only variants of uncertain significance (VUS) among cancer patients." (PMID 36896836, 2023). "Alternative approaches of annotating CAF populations in pancreatic tumours have also been described, including a population of immune-suppressive Lrrc15+ myofibroblasts, and Endoglin (Eng, encoding CD105) positive and negative CAFs, with the latter associated with anti-tumour immunity." (PMID 38678021, 2024). "Microarray data previously published show upregulation of a number of druggable membrane proteins, including CD105 (endoglin), on the 5-FUR pancreatic cancer cell line Panc03.27R–B1V compared to the 5-FUS line Panc03.27S–Nt." (PMID 29258566, 2017). "In addition, in the murine pancreatic cancer model Rip-Tag2, absence of CD105/endoglin in ECs favored an EndoMT process." (PMID 31467544, 2019).
lung carcinoma (18 papers, 2010 to 2024). "Although Hhex is reported to inhibit cell migration and invasion of breast and prostate epithelial cells by upregulating Endoglin expression, the effect and molecular mechanism for lung cancer cell motility regulation remains elusive." (PMID 34321041, 2021). "The in vivo analysis focused on lung cancer because of its high morbidity and mortality and the significance of angiogenesis and endoglin in lung cancer progression and metastasis 56-58." (PMID 33995664, 2021). "There were more lung cancer patients with adenocarcinoma that showed increased ENG expression than patients with squamous cell carcinoma." (PMID 32326402, 2020). "Data from online databases suggest that increased expression of ENG is negatively correlated with the survival of lung cancer patients." (PMID 32326402, 2020). "However, it has been reported that endoglin level changes in lung cancer patients after surgical treatment." (PMID 34587660, 2022). "Increased expression of ENG was negatively-correlated with the survival of lung cancer patients." (PMID 32326402, 2020). "Epigenetic suppression of ENG gene expression has been reported as a common event in some cancers such as esophageal squamous cell carcinoma and lung cancer, and a more aggressive phenotype results from this lack of expression." (PMID 39552710, 2024). "Additionally, in lung cancers, INHA and ENG differed from TGFBR3, as INHA (HR = 1.26, p = 0.00029) and ENG (HR = 1.20, p = 0.0056) were both negative predictors of survival while TGFBR3 (HR = 0.65, p = 3.4E-7) was a strong positive predictor of survival." (PMID 33819300, 2021).